INS (insulin)
Diseases named in the same sentence as INS in open-access papers (continued):
Sharing a sentence is not in itself a finding about the gene and the disease.
cancer (continued). "Genes related to rs117719091 (PFKFB3) and rs140233124 (KIAA0232) play crucial roles in cancer metabolism; PFKFB3 induces glycolysis and activates hepatic stellate cells and then promotes liver fibrosis, and KIAA0232 stimulates insulin secretion to regulate cancer metabolism." (PMID 38003606, 2023). "Third, some studies showed that insulin-treated patients with T2DM had higher mortality from cancer than those without insulin treatment." (PMID 36845740, 2023). "All the mentioned genes take part in the activation of cell growth, proliferation, insulin signaling, and cancer progression, which could result in unwanted effects of ISS in cancer." (PMID 37834191, 2023). "Furthermore, compared to general population, no increased risk for T1DM patients (IRR = 0.31, 95% CI 0.08, 1.24) or for T2DM insulin users (IRR = 0.90, 95% CI 0.64, 1.28) was observed in the group of miscellanea cancer sites." (PMID 35681699, 2022). "There is some evidence that patients with insulin therapy have a higher incidence of cancers when compared to patients with no insulin use, including cancers in colorectum, breast, pancreas, liver, kidney, stomach and respiratory system." (PMID 35222270, 2022). "Increased expression of IGF-2 and the consequent over-activation of this pathway by both insulin and IGF-2 is highly prevalent in cancer cells and may represent an important factor of resistance to various anti-cancer drugs." (PMID 35017650, 2022). "A large population sample found a linear effect of both fasting and post-challenge glucose on cancer mortality, and the result did not change even after the adjustment for fasting insulin." (PMID 35256755, 2022). "Another study demonstrated that despite being capable of stimulating cancer growth, insulin, which is one of the vital anabolic hormones, is not carcinogenic." (PMID 35328822, 2022). "Surprisingly, a 29-year cohort study found that elevated basal insulin level was a negative predictor of cancer prognosis." (PMID 35256755, 2022). "The possible mutagenic effects of insulin or insulin analog and increased levels of IGF-1 might be the potential biological plausibility for the increase risks of cancers." (PMID 35222270, 2022). "Hence, increased signaling via insulin and IGF-1 receptors, and the downstream phosphatidylinositol 3-kinase pathway, are observed in diverse cancers." (PMID 35984550, 2022). "Unlike other types of cancer, PDA risk in insulin users does not increase with a longer insulin duration." (PMID 35252207, 2022). "Unlike the Western diet, low-carbohydrate diets slow cancer by inhibiting insulin/IGF and downstream intracellular signaling pathways, specifically PI3K/Akt/mTOR." (PMID 35745105, 2022). "Insulin, IGF-1 and IGF-2 could activate the PI3K/Akt/mammalian target of rapamycin (mTOR) signaling pathway, thereby promoting the development of cancers." (PMID 35222270, 2022). "As ECM-CAFs originate from resident liver fibroblasts, it is interesting to note that in hepatocytes, Wnt/β-catenin signaling can synergize with insulin signaling through IGF1R, LRP5, and LRP6 34, which were concomitantly enriched in ECM-CAF-cancer cell LR interactions." (PMID 36438498, 2022). "Growing evidence indicates that Cdk5 has important non-neuronal functions in cancer progression, insulin secretion, and immune responses." (PMID 35421092, 2022). "Cell survival and proliferation, proinflammatory cytokine expression and TGR5/STAT3/KLF5 axis activity were measured in normal human gastric cells, cancer cells, and organoid lines derived from C57BL/6, FVB/N and insulin-gastrin (INS-GAS) mice treated with DCA." (PMID 36067404, 2022). "Insulin-independent GLUT1 moves glucose intracellular influx and PKM2 performs a quick catabolism of glucose, both of which are two key steps for aerobic glycolysis to fuel cancer cells with large amounts of ATP." (PMID 36012397, 2022).
cancer (continued). "In addition, inhibition of GLUT-1 results in decreased glucose entry into cancer cells despite insulin, suggesting that GLUT-1 is the primary pathway for insulin-regulated glucose entry." (PMID 35053598, 2022). "In few instances, family member health expenses for conditions, such as cancer, drained family finances and left no money for insulin." (PMID 35436214, 2022). "Unlike insulin secreted exclusively by pancreatic β cells, IGFs, which are produced mainly by the liver, can also be produced by cancer tissues and act through paracrine and autocrine mechanisms." (PMID 35406791, 2022). "Cancer incidence was also found to be significantly increased in non-insulin using diabetic individuals relative to those on insulin therapy, suggesting that the glucose lowering benefits of insulin outweigh its potential mitogenic effects." (PMID 34426491, 2021). "Some clinical studies support the notion that the glucose lowering benefits of insulin override its potential mitogenic effects and reduce cancer risk, whereas a meta-analysis concluded that intensive glycemic control may not significantly influence cancer incidence in T2D." (PMID 34426491, 2021). "A lower dose of pioglitazone seems to have less adverse effects, while not compromising its beneficial effects on blood glucose, insulin sensitivity and cancer." (PMID 33562380, 2021). "According with these studies, in our model neither GH, insulin, nor indomethacin modified cancer growth in vitro or in vivo." (PMID 33664364, 2021). "No study has, to our knowledge, determined the effect of an acute exercise bout on insulin sensitivity, nor the efficacy of exercise to stimulate glucose uptake in muscle in patients with cancer." (PMID 33801684, 2021). "Eight weeks after cancer cell injection and just before the start of treatment, all mice underwent a baseline ITT using the same dose of insulin they received 8 weeks earlier and all mice displayed marked resistance to a decrease in blood glucose following the insulin injection." (PMID 34578801, 2021). "Furthermore, enrichment analysis suggested that Kindlins were primarily correlated with the PI3K-Akt signaling pathway, pathways in cancer, HIF-1 signaling pathway, insulin signaling pathway and mTOR signaling pathway." (PMID 33934696, 2021). "Just before cancer cell injection, at 16 weeks of age mice received an initial insulin tolerance test (ITT) and all mice displayed a strong decrease in blood glucose 30 min after an insulin injection." (PMID 34578801, 2021). "Functional analysis by the PANTHER pipeline on cancer-related MXE showed additional functional enrichments, in signalling process (e.g. oxytocin, adipocytokine and prolactin) and regulatory pathway (e.g. insulin secretion, transcription) (FDR level <0.01)." (PMID 33651795, 2021). "The top five functional annotations were “PI3K-Akt signaling pathway” (P = 5.7E-4), “NF-kappa B signaling pathway” (P = 4.0E-3), “Transcriptional mis-regulation in cancer” (P = 5.2E-3), “TNF signaling pathway” (P = 8.2E-3), and “Insulin resistance” (P = 9.3E-3)." (PMID 33777102, 2021). "Beside cancer cells, we have used several CK2 inhibitors in pancreatic β-cells where we could show an elevated production and subsequent secretion of insulin after CK2 inhibition." (PMID 35056914, 2021). "By enrichment analyses of gene function and protein-protein interaction network construction, we showed that these genes were enriched in several important cancer- or metabolism-related signaling pathways, including PI3K-AKT,RTK-RAS, Notch, Wnt, Hippo, mTOR, AMPK, and insulin signaling." (PMID 34805171, 2021). "In this review, we summarize the role of the circadian clock in regulation of one important metabolic pathway, insulin/IGF1/PI3K/mTOR signaling, and how dysregulation of this metabolic pathway could lead to uncontrolled cancer cell proliferation and growth." (PMID 33672910, 2021).
cancer (continued). "For example, mTORC1 activation decreased in various cancer cell lines following n-3 LCPUFA treatment, but strong mTORC1 activation was observed in muscle tissue from n-3 PUFA supplemented healthy humans or steers only after amino acid and insulin stimulation." (PMID 33657992, 2021). "It is thought that lanreotide could reverse the effects of high blood insulin/IGF1 concentration though activating the somatostatin receptor and inhibiting the PI3K/Akt/mTORC1 pathway in cancer cells." (PMID 35008233, 2021). "Although increased insulin production was a common phenomenon during cancer development, the insulin resistance also occurred in the normal tissues and lead to alterations in carbohydrate and lipid metabolism." (PMID 34488531, 2021). "In addition to the regulatory effect on the insulin signaling pathway, the miR-126/IRS-1 axis is involved in cancer pathogenesis." (PMID 34199293, 2021). "Coupled with altered vasculature as well as a continuous supply of glucose and glycolysis-promoting factors (e.g. insulin), such distinct metabolism of cancer cells promotes their fitness at the expense of their non-oncogenic neighbors." (PMID 33472174, 2021). "Not surprisingly, both elevated concentrations of insulin and IGF-1 are associated with multiple cancer types, including breast, endometrium, pancreas and colon." (PMID 34572814, 2021). "IGF-1 signals some of the same pathways as insulin, including PI3K, ERK, AKT, and mTOR, which could increase cancer cell proliferation and impair apoptosis." (PMID 33477579, 2021). "Additionally, KEGG pathway enrichment included pathways in cancer, HIF-1 signaling pathway, insulin signaling pathway and mTOR signaling pathway." (PMID 33934696, 2021). "Interestingly, a cooperation between insulin/IGF signaling and integrin-mediated adhesions were reported in other cell types, such as Chinese hamster ovary cells, hepatocytes, or cancer cells." (PMID 32934005, 2020). "Besides, clinical evidence also suggests that elevated insulin and IGF-1 levels favor the progression of a variety of cancers." (PMID 32512898, 2020). "Binding of insulin or IGF-1 to their receptors activates many signaling pathways, which can promote the proliferation, invasion, and metastasis of cancer cells, inhibit apoptosis, and lead to the development and progression of many types of cancer cell." (PMID 31942181, 2020). "Among colon cancer patients with DM who receive antidiabetic drug therapy, patients who use insulin have shorter overall survival and cancer-specific survival than patients who do not." (PMID 33255227, 2020). "No prior publications were found describing the effects of insulin on the expression level of NR2F2 in cancer cells." (PMID 32631390, 2020). "The observed association may be explained by a healthier profile of plasma biomarkers of inflammation, insulin, and hormonal response with greater adherence to the WCRF/AICR cancer prevention recommendations." (PMID 32668662, 2020). "The insulin and IGF-1 receptors (IGF-1R) are homologous and often overexpressed in cancer cells." (PMID 33198356, 2020). "The insulin/IGF system is likewise involved in cancer cell metabolism, resistance to cancer drugs, and cancer stem cell (CSC) phenotypes, which emphasize the significance of this system in the monitoring networks of the development and progression of cancer." (PMID 32500027, 2020). "As recently published, insulin and insulin-like growth factor-1 (IGF1) activates several pro-mitogenic and pro-angiogenic signaling mechanisms and thus support pathogenesis and the progression of several cancers, including breast cancers." (PMID 32883003, 2020). "Stimulation of glucose utilization and fatty-acid oxidation by adiponectin occurs through activation of AMPK which is an insulin-independent pathway that regulates energy metabolism, though Hypoxia-inducible factor-1α (HIF-1α) regulates glycolysis in cancer cells by inactivation of AMPK." (PMID 32082261, 2020).
cancer (continued). "Excess insulin directly or indirectly regulated the activity of insulin-like growth factor-1 (IGF-1), which was an important cytokine that influenced the development and progression of cancer." (PMID 32709224, 2020). "Although at present no clinical studies have shown that this strategy provides any clinical benefits for patients with tumors overexpressing the DRR1 and the insulin-IGF-I system, these results may help to develop novel therapeutic approaches for cancer." (PMID 32252327, 2020). "This kinase could also be involved in the regulation of basal insulin secretion, especially because IGF1R inhibition has been shown to activate YES proteins in cancer cells." (PMID 32934005, 2020). "Therefore, GHR inhibition appears to be a safer and validated point of intervention to suppress cancer growth and especially drug resistance, as well as in reducing circulating IGF-1 levels and improving insulin sensitivity." (PMID 33291663, 2020). "To assess if PpIX and BPD inhibit TrxR activity in cancer cells also, we treated Panc1 cells with the increasing concentrations of PpIX or BPD for 6 h and assayed the activity using the end point Trx-dependent insulin-reduction assay." (PMID 30820346, 2019). "Moreover, metformin was found to reduce insulin level, inhibit insulin/IGF signaling pathways, and modify cellular metabolism of insulin in normal and cancer cells." (PMID 31139216, 2019). "Cancer cells expressing constitutively active phosphatidylinositol-3 kinase (PI3K) are proliferative regardless of the absence of insulin, and they can form dietary restriction (DR)-resistant tumors in vivo." (PMID 30984619, 2019). "Lowering insulin and insulin-like growth factor 1 (IGF-1) levels that stimulate cancer growth could be important features of metformin's mode of action." (PMID 30147674, 2018). "Only 15% of patients changed their DM therapy or began insulin therapy within a year of the cancer diagnosis, although data were not recorded for 24% of patients." (PMID 29255620, 2018). "This failure may not only be due to the complexity and homology that is shared by Insulin and IGF receptors, but also due to the complex stroma-cancer interactions in the pancreas." (PMID 29475434, 2018). "These reviews suggest that the insulin level is not a surrogate marker of cancer development, thereby indicating a unique mechanism of metformin activity in cancer." (PMID 30208162, 2018). "Regulation of telomeres and the insulin/PI3K pathway both have roles in aging and cancer development but have not been functionally linked." (PMID 29097657, 2017). "The mechanisms for the angiogenic role of insulin-sensitizing drugs on cancer development are not well understood." (PMID 28424632, 2017). "The molecule mechanisms of metformin's anti-cancer activities mostly rely on its ability to inhibit the LKB1-AMPK-mTOR signaling pathway and the cell division, to promote apoptosis and autophagy and down-regulate the circulating insulin." (PMID 28903435, 2017). "Taken together, and given the impact of the insulin/IGF pathway in cancer drugs resistance mechanisms, the modulation of this pathway might be an attractive strategy to reverse cancer therapy resistance in various types of cancer." (PMID 28880250, 2017). "Therefore, cancer cells of early-biopsy cultures must be weaned off of EGF and insulin prior to drug testing." (PMID 29241554, 2017). "Hence, we concentrated on the main mechanisms proposed for the anti-aging effects of CR: modulated insulin/IGF-1, mTOR, NF-ĸB and Sirtuin signaling, reduced oxidative stress, the disposable soma theory, anti-cancer mechanisms and increased autophagy." (PMID 28768896, 2017). "Telomeres and the insulin/PI3K pathway are considered hallmarks of aging and cancer." (PMID 29097657, 2017). "A combination of these compounds with insulin may be of potential relevance for the support of T2DM treatment and help in the prevention of co-morbid diseases such as cancer." (PMID 29231877, 2017).
cancer (continued). "The flow cytometry analysis showed that insulin had no significant impact on the ratio of apoptosis in all tested cancer cell lines." (PMID 29371977, 2017). "Insulin is an anabolic hormone able to increase IGF-1 synthesis and activity and IGF-1 in turn may promote cancer development by inhibiting apoptosis, stimulating cell proliferation and sex-steroid synthesis." (PMID 28114909, 2017). "Furthermore, PPAR-γ agonists downregulate key pathways of the insulin/IGF axis, such as PI3K/mTOR, MAPK, and GSK3β/Wnt/β-catenin cascades, which regulate cancer cell growth, proliferation, cell reprogramming, and differentiation." (PMID 28275367, 2017). "Moreover, ligand-dependent and independent activation of estrogen receptors increases insulin/IGF-mediated growth effects in several tumors, such as neuroblastoma, pituitary adenomas, and cancers from breast and prostate." (PMID 28275367, 2017). "Interestingly, evidence points towards the existence of a regulatory circuit between glycosylation, insulin/IGF system and cancer." (PMID 28880250, 2017). "Although inflammation is a powerful driver of tumor growth, it is the aim of this review to focus on the connection between insulin/IGF-1 signaling and cancer, and discuss possibilities to modulate these interactions through DR and pharmaceutical interventions to improve cancer outcomes." (PMID 26878387, 2016). "The canonical pathway analysis showed that top 5 pathways (according to most significance in database) are involved in invasive subclone A253-5 cells including arginine and proline metabolism, general pathways in cancer, TGF-beta signaling, focal adhesion and insulin signaling." (PMID 27391030, 2016). "The postulated anti-tumor effects of metformin are complex, but they appear not to be insulin mediated, but possibly through inhibition of cancer stem cells." (PMID 27599544, 2016). "Furthermore, insulin and the insulin-like growth factor (IGF) axis have a number of effects on cancer cells." (PMID 26983499, 2016). "Furthermore, it was important to get some insights into alterations of the insulin/IGF network during cellular transformation, to try to develop new approaches against cancer in the future." (PMID 27849005, 2016). "High insulin and insulin-like growth factor (IGF) may stimulate insulin-mediated mutagenesis and cancer cell proliferation and metastasis." (PMID 27760202, 2016). "Collectively, these data indicated that insulin down-regulates MTMR7 protein as an endogenous inhibitor of growth factor receptor signaling, thereby establishing a potential vicious cycle promoting the proliferation of cancer cells." (PMID 27409167, 2016). "This creates a situation whereby insulin analogues with increased affinity for IRA and/or IGF1R may increase the cancer hazard." (PMID 25848982, 2015). "Despite the well-characterized role of HSF1 in cancer development and progression, in the context of PKCθ activation and the inhibition of the insulin pathway, non-heat-shock HSF1 activation appears to provide a therapeutic advantage." (PMID 26298773, 2015). "This review recapitulates the relevant aspects of this functional cross-talk between the insulin/IGF and the estrogenic GPER transduction pathways, which occurs in various cell types and may account for cancer progression." (PMID 25798130, 2015). "Thus, TRIP-Br1 expression seems to be at least in part increased by insufficient insulin survival factor in MCF7 and MDA-MB-231 cancer cells under the condition of serum starvation." (PMID 26334958, 2015). "Cross-pathway compensation between insulin and IGF1 signalling has been observed in cancer systems, so that downregulation of multiple pathways, as occurs in ageing brain, may be needed to significantly impair astrocyte survival." (PMID 26297026, 2015).